KRAS (KRas proto-oncogene, GTPase)
Diseases named in the same sentence as KRAS in open-access papers (continued):
Sharing a sentence is not in itself a finding about the gene and the disease.
melanoma (continued). "Remarkably, in mice with the KRAS* PDAC, 36–43% had a durable response, while in mice with the B16F10 melanoma, 20% had a durable response." (PMID 30796212, 2019). "One possible strategy to delay the clinical onset of resistance is to co-administer drugs that inhibit the ability of initial NRAS or KRAS-mutant clones to proliferate, as has been suggested previously with 17-AAG and melanoma." (PMID 29481571, 2018). "Clinical trials showed that inhibitors of MEK1/2, downstream of the RAS pathway, had promising efficiency in KRAS mutant NSCLC and NRAS mutant melanoma." (PMID 29285234, 2017). "Markers tested by NGS mainly provide information relevant for using targeted therapy (breast: HER2 IHC; colon: KRAS; lung: EGFR; and melanoma: BRAF)." (PMID 28371134, 2017). "In support of this, c-Fos has recently been described to regulate YAP1 transcriptional activity in the context of KRAS-driven cancers and AP-1/TEAD were found to act as regulators of the invasive gene network in melanoma." (PMID 26295846, 2015). "BRAF V600E PDA cell line was equally sensitive as MNT1 melanoma cells to the FDA-approved BRAF inhibitor PLX-4032, while KRAS driven cells (PL45) are resistant." (PMID 25855536, 2015). "A thyroid sample and a CRC sample each had one false positive in NRAS, whereas one melanoma sample had two false negatives in BRAF and a false positive in KRAS." (PMID 23991070, 2013). "Members of the Ras/RAF/MEK/ERK pathway, in particular KRAS and BRAF, are frequently deregulated in several cancers including melanoma, colorectal (CRC), non-small cell lung cancer (NSCLC) and pancreatic." (PMID 22343622, 2012). "However, despite the lower frequencies, BRAF, NRAS, KRAS, and KIT are somatic SNVs identified in canine melanomas, accounting for 1.8% (5/272), 8.0% (25/311), 13.1% (27/206), and 22.9% (16/70), respectively." (PMID 38397192, 2024). "The oncogenic RAS genes in melanoma cells include NRAS, KRAS, and HRAS." (PMID 36901857, 2023). "One study comparing NAM (n = 54) and non-NAM acral melanoma (n = 78) revealed that, among common melanoma driver genes, mutations in KIT and KRAS were predominantly found in NAM, whereas those in BRAF and NRAS occurred almost exclusively in acral melanoma." (PMID 36983205, 2023). "Mutant KRAS appears to be involved in over 90% of PDAC, about 50% of CRC, about 30% of NSCLC and to a lesser extent in other tumors, while mutant BRAF has primarily been observed in melanomas." (PMID 35965494, 2022). "These subtypes are represented by BRAF mutant melanomas, which account for approximately 50% of melanomas; NRAS-, KRAS-, and HRAS-mutant melanomas, which are about 25%; NF1-mutant melanomas (15% of melanomas); and triple-wild-type melanomas, which account for the remaining 10% of cases." (PMID 35563772, 2022). "MEKi, ERKi and KRAS ablation strongly elevate protective autophagy flux via LKB1-AMPK-ULK1 axis, inhibition of which sensitizes tumor cells to KRAS signaling inhibition in PDAC, melanoma and CRC models 162, 188, 189, implying autophagy as a common surviving mechanism." (PMID 35966590, 2022). "Along with the KRAS inhibitor sotorasib, the proof-of-concept of tunlametininb as a therapeutic approach towards NRAS mutant melanoma may broaden the once challenging area of RAS mutant cancer." (PMID 36386136, 2022). "Trametinib and VX11E, but not SHP099, had substantial activity across melanoma cell lines enriched in the BRAF mutant as well as some mild activity in KRAS mutant tumors such as pancreas." (PMID 35905710, 2022).
melanoma (continued). "Typically, these panels only cover driver mutations in genes known to be involved in melanoma, such as BRAF, NRAS, KRAS, KIT, GNAQ, and GNA11, and do not include genes that have been recently found by WES/WGS studies." (PMID 36431075, 2022). "The first trial is currently enrolling both NRAS mutant cutaneous melanomas and KRAS or BRAF mutant non-small cell lung cancers progressed after standard of care therapy, while the second one is focused on pre-treated BRAF or NRAS mutant melanomas." (PMID 34071228, 2021). "Targeting KRAS and HRAS mutations in melanomas is not currently being pursued due to the lack of insight on the biological impact in melanomagenesis." (PMID 34831002, 2021). "In a word, compared with gynecologic melanoma, non-gynecologic melanoma harbored distinct mutation rates in KIT, BRAF, SF3B1, KRAS and NRAS genes." (PMID 34102999, 2021). "BRAF- or KRAS-driven colorectal cancer and BRAF-driven melanoma exhibit increased glycolysis, and inhibition of BRAFV600E suppressed the levels of glycolysis in BRAF-driven melanoma." (PMID 34298710, 2021). "We observed that gynecologic melanoma harbored distinct mutation rates in c-KIT, BRAF, SF3B1, KRAS and NRAS genes compared with non-gynecologic melanoma." (PMID 34102999, 2021). "While KRAS is the overall dominant gene that is coaltered, HRAS contributed to most coalteration cases in bladder cancer, and NF1 coalteration preferably occurs in melanoma and endometrial cancer." (PMID 33507258, 2021). "To determine whether the use of our system can be extended to the analysis of multiple loci, we designed a sgRNA library for three genes (MAP2K1, KRAS, and NRAS) related to vemurafenib resistance in melanoma." (PMID 32242071, 2020). "Alterations of the CDK4/6 signaling pathway is observed in different types of melanoma, concomitantly with NRAS, KRAS or BRAF; thus the genetic profiling of CDK4/6 may provide insights for the targeted treatment of various types of melanoma." (PMID 33233603, 2020). "The lack of confirmed objective responses in BRAF mutant CRC, in contradistinction to melanoma, to the RAF dimer inhibitor lifirafenib which inhibits all RAF isoforms as well as EGFR and KRAS supports this hypothesis." (PMID 32922659, 2020). "However, in C8161 cells with concomitant KRAS/c-MYC dysregulation, TTM reversion of melanoma toxicity by DSF + OPT was diminished." (PMID 30792807, 2019). "We report data from the testing of our novel PDE8A – C-Raf disrupter/HOXD12 conjugate (from here on, named PPL-008) in MM415, a B-Raf inhibitor resistant malignant melanoma cell line (MM415; BRAF wt, KRAS wt, NRAS Q61L) and in an MM415 melanoma murine xenograft model." (PMID 30909892, 2019). "RAC1 function is also known to be essential in KRAS induced tumor formation, and in KRAS oncogene addiction, so the potential exists for SRF/MRTF inhibition to be explored in a far greater range of tumors than just RAC1P29S melanoma." (PMID 31257073, 2019). "NGS revealed 118 (26%) of 446 melanomas with no mutation, 42% with BRAF mutations, 25% with NRAS mutations, 4.9% with KIT mutations, and 2.0, 2.7 and 2.7% with HRAS, KRAS and PIK3CA mutations, respectively." (PMID 31277584, 2019). "The genomic landscape of melanoma, performed by The Cancer Genome Atlas (TCGA) on 333 melanoma samples delineated 4 genomic subtypes, i.e., triple wild-type (WT), BRAF mutant, NRAS, HRAS or KRAS mutant, and NF1 mutant, as well as three transcriptomic subclasses, i.e., immune, keratin and MIFT-low." (PMID 29743104, 2018). "Sequencing of mutation hotspots in five melanoma driver genes (BRAF, NRAS, KRAS, GNAQ, GNA11) did not reveal any changes in 9/11 patients." (PMID 30558566, 2018). "It is also possible that NRAS may activate different signaling pathways from KRAS and HRAS, an idea supported by the observation that NRAS has greater transforming activity than KRAS in experimental models of melanoma." (PMID 29349077, 2017).
melanoma (continued). "Notably miR-340 is able to affect the expression of 39 out of 45 total RAS-RAF-MAPK components, such as BRAF, KRAS, NRAS and MYC, thus reducing melanoma cell growth and migration." (PMID 28118616, 2017). "Although NRAS mutations have been reported in 14% of human melanoma cell lines and 15–25% of melanoma clinical specimens, nevertheless, HRAS and KRAS mutations are not common in melanoma." (PMID 25695059, 2015). "Mutations were also identified in brain metastases from non-breast primaries in EGFR (3/9 - 33%; two lung and one kidney), HRAS (1/9 - 11%; lung), KRAS (2/9 - 22%; one colon and one lung), NRAS (3/9 - 33%; two lung and one kidney) and PIK3CA (2/9 - 22%; one melanoma and one lung)." (PMID 20604919, 2010). "Unlike KRAS and BRAF mutations, NRAS mutations may be more significant in melanoma than CRC, but can still be seen in both cancers." (PMID 40447784, 2025). "Meningeal melanocytomas and melanomas do not usually harbor HRAS, KRAS, BRAF, or KIT mutations." (PMID 39061148, 2024). "In addition, class 3 BRAF mutations were more prevalent in HRAS-mutant salivary gland (5%), and bladder (9%), and melanoma (11%) cancers, whereas none were present in the respective KRAS- and NRAS-mutant tumors (p<0.05 for all)." (PMID 37503077, 2023). "The preliminary indication of antitumor activity in BRAF-mutated melanoma is promising although further clinical development of single agent use in this setting in tumors that do not harbor RAF fusions (e.g., those with KRAS or NRAS mutations) is likely to be limited." (PMID 37219686, 2023). "Notably, we observe a significant increase in the basal levels of both EGFR and PD-L1 expression in KRAS G13D A375 melanoma cells but not in NRAS Q61K cells." (PMID 36358868, 2022). "Notably, KSR2 has also been linked to MAPK pathway reactivation and resistance to BRAF+MEK inhibition in melanoma cells, thus suggesting that the roles of KSR1 or KSR2 in modulating the response to KRAS/MAPK pathway inhibition may have been underestimated." (PMID 35313064, 2022). "Statistical analysis showed that the degree of pigmentation, mitotic count, degree of nuclear atypia or histomorphological type of digital melanomas, as well as the survival time, were neither significantly associated with RAS mutations in general nor with KRAS mutations." (PMID 35202309, 2022). "Thus, targeting wild-type KRAS might represent a promising therapeutic strategy to enhance treatment response in both HCC and melanoma." (PMID 31906510, 2020). "Lenalidomide has thus far had no clinical success in KRAS mutant cases nor melanoma." (PMID 33274713, 2020). "Moreover, combinatory approaches of KRAS inhibition (applying miR-622 or RNAi-mediated or pharmacologic KRAS-inhibition) and sorafenib in HCC or vemurafenib in melanoma, respectively, revealed synergistic anti-tumorigenic effects and reverted chemoresistance in both cancer types." (PMID 31906510, 2020). "TTM was not toxic against V600E-mut-BRAF A375 and G12D-mut-KRAS/high c-myc C8161 melanoma cells." (PMID 30792807, 2019). "This either means that the same rules do not apply in melanoma, that oncogenic KRAS and NRAS differ or that the mechanism of action of karonudib extends outside MTH1 inhibition, e.g., the proposed microtubule disruption caused by inhibitors of the same class as karonudib." (PMID 30042422, 2018). "When we crossed this list with the list of down regulated mRNAs in miR-377-expressing melanoma cells, we found 4 putative transcripts with miR-377-binding sites: E2F3 (a putative target of miR-377 in 6 out of 10 software), MAP3K7 (in 4 out of 10), KRAS (in 5 out of 10) and CDK6 (in 5 out of 10)." (PMID 25889255, 2015). "However, mutations in NRAS (~30%), but not KRAS (3%) or HRAS (2%), are common in melanomas." (PMID 36901857, 2023).
melanoma (continued). "Personalized timing based on assessment of mutant BRAF or KRAS amplification levels by sampling cfDNA for example, may be required to better elicit MAPK hyperactivation to forestall drug resistance using an intermittent dosing strategy in lung and melanoma patients." (PMID 36418460, 2022). "Notably, synergistic effects of KRAS/RAF/MEK/ERK inhibitors combined with autophagy inhibitors is not restricted to KRAS-driven PDAC models, but is also observed in NRAS-mutated melanoma, BRAF-mutated colorectal patient derived xenografts (PDXs) models and BRAF-mutant thyroid cancers." (PMID 32878084, 2020). "WGS studies have suggested that TWT melanomas, commonly of the AM subtype, are more likely to have focal amplifications of CCND1, MDM2, KIT, and KRAS, as well as CDK4 and CDK6, than non-TWT melanomas." (PMID 39858514, 2025). "Furthermore, besides SF3B1 and KIT mutations, other variants have been described in the context of mucosal melanoma, including amplifications of CCND1, MDM2 and KRAS, however this was not assessed this cohort and could represent a source of additional driver eventsin this cohort." (PMID 30847022, 2019). "Additionally, when we plotted the top 65 DEGs, we noticed that sample clustering was independent of mutations in the RAS (KRAS, NRAS, and HRAS) and NF1 genes, which have been described to modify gene expression patterns in melanoma, avoiding expression bias that might be caused by those genes." (PMID 30242167, 2018). "Despite recent advances in understanding Ras signaling biology and the revolution in therapies for melanoma using BRAF inhibitors, no targeted agents have been effective in KRAS‐mutant cancers, mainly due to activation of compensatory pathways." (PMID 28173629, 2017). "Finally, PD-L1 expression is constitutively elevated in KRAS G13D but not in NRAS Q61K or MEK1 Q56P A375 cells, pointing to a possible role for immune checkpoint inhibition in melanomas carrying this specific biomarker." (PMID 36358868, 2022).
adenoma (328 papers, 1991 to 2026). A neoplasm arising from the epithelium. "At the molecular level, the adenoma-carcinoma sequence pathway is characterized by an abundance of KRAS mutations and somatic copy number alterations." (PMID 41488286, 2026). "In our FAP cohort, the frequency of KRAS mutation in patients with HG adenomas or carcinomas was higher than that in patients with sporadic tumors." (PMID 41488735, 2025). "As the lesion enlarges, further mutations frequently affect oncogenes such as KRAS, enhancing proliferative signaling and supporting the transition to more advanced adenomas with high-grade dysplasia." (PMID 41228231, 2025). "CRC develops through two major molecular pathways: the classic adenoma-adenocarcinoma sequence (~70% of cases) and the serrated neoplasia pathway (SNP, ~30%), characterized by hypermethylation of CpG islands and KRAS mutations." (PMID 40520898, 2025). "Second, it explored the changes in microbial composition from adenoma to adenocarcinoma and described the correlation between KRAS mutations and microorganisms." (PMID 40485603, 2025). "In adenomas, KRAS‐mutated types showed a higher enrichment of genus Peptostreptococcus and Leuconostoc and a lower abundance of genus Bacillus and Haemophilus compared to wild‐type adenomas." (PMID 40485603, 2025). "It was previously thought that a KRAS mutation was specific only to CRCs developing from Vogelstein’s classical adenoma–carcinoma sequence." (PMID 40572720, 2025). "In adenomas, the KRAS c.34G>T mutation was present in 6/9 (66.7 %) and 2/27 (7.4 %) of the biallelic MUTYH and non-hereditary adenomas, respectively (p-value=3.1 × 10–2)." (PMID 39793275, 2025). "One of the largest differences was detected in the prevalence of KRAS mutations, which are significantly more frequent in monoclonal adenomas and comparable to the frequency found in established CRCs." (PMID 40451939, 2025). "Loss-of-function mutations in the tumor suppressor gene APC initiate neoplastic transformation, while subsequent activating mutations in the oncogene KRAS are frequently associated with the progression from benign adenoma to dysplastic adenocarcinoma." (PMID 41294868, 2025). "Significantly, the KRAS mutation frequency is markedly higher in LST-G adenomas relative to protruded adenomas (PAs), whereas it is diminished in LST-NG adenomas." (PMID 41018078, 2025). "They observed that certain adenomas shared methylation profiles with cancers, including intergenic and intragenic CpG changes and driver mutations in KRAS and APC, suggesting that epigenetic reprogramming begins early and persists through progression." (PMID 40806210, 2025). "KRAS mutations, in comparison, were found in 20/70 (29%) adenomas, all but one of which were TAs with LGD." (PMID 38546397, 2024). "Consistent with the Vogelstein model, we observed that in all simulations where neoplastic phenotypes emerged, cells initially assumed the adenoma phenotype (i.e., KRAS mutation)." (PMID 39593869, 2024). "Studies investigating the influence of specific KRAS mutations in patients with early-stage adenoma would further raise our understanding on the specific role of KRAS mutations on the pathogenesis of CRC." (PMID 38464238, 2024).